KLK3 (kallikrein related peptidase 3)
Diseases named in the same sentence as KLK3 in open-access papers (continued):
Sharing a sentence is not in itself a finding about the gene and the disease.
cancer (707 papers, 1999 to 2026). A tumor composed of atypical neoplastic, often pleomorphic cells that invade other tissues. "This suggests the role of KLK3 in several types of cancer, making it a potential diagnostic marker for cancer in general." (PMID 36140706, 2022). "KLK3 expression is often reduced upon loss of differentiation in cancer cells and low KLK3 levels in the prostate are associated with poor prognosis." (PMID 34948344, 2021). "Recently, a glycan-specific immunoassay for cancer-related KLK3 variants has been established." (PMID 27898009, 2016). "The understanding of glycan functions becomes highly significant in proteomic and glycomic studies, which demonstrated that cancer-associated proteases, such as kallikrein-related peptidase 3, exhibit strongly altered glycosylation patterns in pathological cases." (PMID 27898009, 2016). "For example, SNPs in the KLK3 promoter may account for individual variation in serum prostate-specific antigen levels and even cancer susceptibility." (PMID 17242704, 2007). "In addition, lncRNA ASLNC04080 was demonstrated to be correlated to KLK3, which could serve as a diagnostic marker for cancers." (PMID 31007611, 2019). "Machine learning identified five potential diagnostic biomarkers (COLEC12, TMCC1, CEP55, KLK3, COL4A1) with an AUC of 0.903, which are implicated in immune modulation and cancer progression." (PMID 40427030, 2025). "Studies of cancer‐specific transcripts in whole blood as non‐invasive markers of disease by RT‐PCR date back to the 1990s, including KLK3 in PCa." (PMID 39840448, 2025). "Overexpression of KLK3 degrades the extracellular matrix and thus expands cancer tissue, and correlates with increased angiogenesis." (PMID 40190563, 2025). "Yet, the mapped genes were highly relevant to PCa etiology and included known cancer drivers LDLRAD4, GMNN, COL1A1, CD38, PTPRN2, GTSE1 and CAMK2N1 in the risk signature and KLK2, AR, KLK3, SPDEF in the relapse signature." (PMID 33845808, 2021). "We were interested if our qRT-PCR assay detects relevant numbers of leukocytes (CD45 positive) and cancer cells (KLK3 positive) in urine and performed a simple dilution experiment." (PMID 32630458, 2020). "Genes that regulate critical mechanisms in other cancers and which are expressed in prostate cancer include Kallikrein-related peptidase 3 (KLK3), also referred to as prostate surface antigen (PSA)." (PMID 27609145, 2016). "This family of proteases, which includes one of the most useful cancer biomarkers, kallikrein-related peptidase 3 or PSA, also has a protective effect against cancer promoting apoptosis or counteracting angiogenesis and cell proliferation." (PMID 26783378, 2015). "The potential of KLKs as cancer markers has been suggested for several members of this protease family, particularly for kallikrein-related peptidase 3 or prostate-specific antigen (PSA)." (PMID 26783378, 2015). "We found also several genes underexpressed in subset of cancer samples like KLK3, FOLH1, SPON2, A2M, and PCP4." (PMID 22811706, 2012). "Specifically, we identify putative miRNA target sites in the 3′UTRs of BMPR1B, KLK3, and SPRY4 that are disrupted by both somatic and germline mutations and, also, are in linkage disequilibrium blocks with high scoring markers from cancer association studies." (PMID 23091610, 2012). "As expected, KLK3 mRNA levels dropped in the stage of cancer progression that was RAD versus AS (58%, 49%, and 37%), and rose in the stage of cancer progression that was CR versus RAD (229%, 349%, and 264%) for mice 13R, 15N, and 13N, respectively." (PMID 20868494, 2010).
cancer (continued). "The KLK3 and FOLH1 proteins were targets for diagnostic and therapeutic agents; the remaining genes were targets for treatment or palliative agents, mostly in approved or investigational status in various types of cancer." (PMID 39595075, 2024). "Additionally, we found that the “Cancer cells” possessed the highest KLK3 score, a relatively high AR score, and a lower NKX3‐1 score compared to the other subsets." (PMID 38483933, 2024). "Measurement of KLK3 protein and KLK3 mRNA levels showed that the ability of serum to induce KLK3 production in cancer cells was proportional to serum progesterone levels, with the greatest stimulation occurring with serum containing more progesterone (days 22–24 of the menstrual cycle)." (PMID 34444582, 2021). "To gain some insight into the functional relevance of the observed association between AIM and PSA expression, we evaluated the expression profile of PSA/KLK3 across 32 cancer types (n = 20,386) at different clinical stages using the Institute of Cancer Research (ICR)-curated dataset." (PMID 34572412, 2021). "However, a negative regulatory role for KLK3 in cancer has also been suggested because this protease can activate latent transforming growth factor-β (TGFβ), a known suppressor of growth and promoter of apoptosis." (PMID 26783378, 2015). "Compared to the luminal-like types, the non-luminal-like cancer cells show less features of secretory differentiation such as decreased expression of KLK3 and AR, and expression of markers associated with more primitive cell types." (PMID 21605402, 2011). "Therefore, the 37-gene signature in urine samples represents prostate tissue gene expression and might be useful to distinguish advanced PCa (higher PCA3 and KLK3 levels in cancer) as well as to detect PCa itself." (PMID 32111915, 2020). "The urine proteome profile of PCa and cancer-free subjects was analyzed by two software packages and 18 dysregulated proteins, of which 5 (TTR, EFEMP1, CDH1, SECTM1, KLK3) common to both software, were found." (PMID 35454907, 2022). "Many pathways involved in cancer were identified to be enriched by genes when METTL3 is depleted, including genes involved in the PCa KEGG pathway, such as TMPRRS2 and KLK3." (PMID 36291932, 2022). "Genes such are GSTA4, GSTO2, KLK3, PGF were down-regulated and E2F2, MMP9, PIM2, VEGFC are up-regulated in all cancer nodules." (PMID 34209090, 2021). "Among its related pathways are Transcriptional misregulation in cancer and Activated PKN1, which stimulates transcription of AR (androgen receptor) regulated genes KLK2 and KLK3." (PMID 33613644, 2021). "Considering age, several genes responsible for inflammatory protein secretion/activation (KLK3, EDN3), cell-adhesion (PI4KA, AHSAI1) and cancer-related proteins (KLK3, FGFR1/2, PRKACA, and RAC2) were also modulated in AYA-RMS." (PMID 31533233, 2019). "Transcriptional control of key players of cancer and AR signaling by KDM3A such as KLK3, NKX3-1, MYC were validated by chromatin immunoprecipitation coupled with quantitative real time polymerase chain reaction (ChIP-qRT-PCR)." (PMID 28416760, 2017). "Many other cancer-related genes show distinct alternative splicing profiles in cancers, including BRCA1, BRCA2, MDM2, KLK3 (also named prostate-specific antigen, PSA), and fibroblast growth factor receptors (FGFRs)." (PMID 28257090, 2017). "Since several KLKs exhibit altered expression in various cancers, they are used as biomarkers, e.g., KLK3/PSA (prostate specific antigen), and investigated as drug targets." (PMID 27898009, 2016). "Ingenuity analysis identified a group of 7 genes (BEX1, FBLN1, FGD3, HBEGF, KLK3, KLK6, and WNT5B) related to cancer, cellular function and maintenance, cellular growth, invasion, as well as proliferation with P < 0.001-0.05." (PMID 21134280, 2010).
cancer (continued). "As can be inferred from the array signal intensity levels, expression of the major functional prostatic secretory proteins ACPP, AZGP1, KLK2, KLK3, and MSMB was down-regulated in the cancer cells compared to the luminal cells." (PMID 20021671, 2009). "While very few EST clones were retrieved from the 14 EST cancer libraries (nine for KLK8, two for KLK3, and one for each of the rest), EST clones were much more detectable in normal libraries." (PMID 14710225, 2004). "The serum concentrations of KLK3 do not correlate with the expression in the prostate as the increased serum levels in cancer are due to an increased release of KLK3 into blood." (PMID 34948344, 2021). "The results for KLK3 were inconclusive, as low expression was detected in only one normal library, but not in cancer libraries." (PMID 14710225, 2004). "However, the KLK3 levels in these mice were orders of magnitude lower than those in the human prostate and the potential role of KLK3 in cancer progression was not addressed." (PMID 34948344, 2021). "Studies with these mice suggest that KLK3 is not able to initiate cancer." (PMID 34948344, 2021). "Owing to its very large (negative) contribution to the cancer phenotype in all three nodules and its antiangiogenic activity, restoration of the normal expression of KLK3 may be instrumental for the normal phenotype recovery." (PMID 34209090, 2021). "From these studies, we can see that although KLK3 is not directly related to BC, the functions in other cancers may imply its potential role in BC." (PMID 29142286, 2017). "This analysis shows that despite the greater expression difference in normal versus cancer tissues, the new markers are unlikely to be superior to KLK3/PSA given their widespread expression in other normal and neoplastic tissues as well as in tissues affected by other diseases." (PMID 24477410, 2014). "SAA did little to increase the ability of KLK3 to distinguish between cancer and noncancer, but pairwise Mann–Whitney U analysis suggested it may have a role in distinguishing different stages of cancer and should not be dismissed as a potentially useful biomarker in a future biomarker panel." (PMID 27685442, 2016). "Unlike KLK3 and ACPP, luminal expression of MSMB appears not to be regulated by stromal influence, and is known to be down-regulated in cancer cells." (PMID 20021671, 2009).
adenocarcinoma (37 papers, 2010 to 2025). A common cancer characterized by the presence of malignant glandular cells. "The in vivo maintained LuCaP 35 was derived from a lymph node metastasis and shows features of a prostate-specific antigen (PSA/KLK3)-producing adenocarcinoma." (PMID 21605402, 2011). "As one of the downstream genes of AR, KLK3 was also negatively stained in PGCA, suggesting that the elevation of PSA was derived from the coexisting adenocarcinoma." (PMID 40873563, 2025). "Rather, nearly every focus showed strong enrichment for genes in the AR-dependent adenocarcinoma gene group, which included AR, NKX3-1, and KLK3." (PMID 40906535, 2025). "On the contrary, AR expression as well as AR driven gene signature such as expression of KLK3, or Nkx3.1 decreased in C4-2BER and DKD (representing t-NEPC) cells as compared to adenocarcinoma C4-2B and C4-2 cells respectively." (PMID 38168280, 2023). "Specifically, in adenocarcinoma, FOXA1 binds to regulatory elements of prostate-lineage genes such as KLK3, HOXB13, and NKX3-1." (PMID 34884545, 2021).
KLK3 also shares sentences with these, for which no sentence is quoted: metastatic disease (54 papers); colorectal cancer (37); diabetes (30); lung carcinoma (29); colon carcinoma (24); Obesity (21); hepatocellular carcinoma (20); Hypertension (20); liver cancer (16); bone metastasis (15); melanoma (13); prostate disorder (13); Anxiety (12); erectile dysfunction (11); squamous cell carcinoma (11); anemia (10); bowel cancer (7); acinar adenocarcinoma (6); cardiovascular disease (6); skin cancer (6); metabolic syndrome (5); myocardial infarction (5); periodontitis (5); sexually transmitted infections (5); small cell carcinoma (5); chronic obstructive pulmonary disease (4); COVID-19 (4); gastric cancer (4); infection (4); multiple myeloma (4).
A further 214 diseases each share a sentence with KLK3 in 4 papers or fewer.